CACNA1G (calcium voltage-gated channel subunit alpha1 G)
Diseases named in the same sentence as CACNA1G in open-access papers (continued):
Sharing a sentence is not in itself a finding about the gene and the disease.
Cognitive impairment (3 papers, 2020 to 2023). Abnormal cognition is characterized by deficits in thinking, reasoning, or remembering. "Strikingly, the additional decrease in Cav3.1 expression in AD patients characterizes Cav3.1 (CACNA1G) as a critical factor of Ca2+ homeostasis and facilitates cognitive impairment." (PMID 35408817, 2022).
glioma (3 papers, 2008 to 2021). A benign or malignant brain and spinal cord tumor that arises from glial cells (astrocytes, oligodendrocytes, ependymal cells). "Six of those genes were found in three of the six most enriched ‘glioma TADs’: 2160 (CDK4, TSFM, TSPAN31, B4GALNT1), 2337 (NFATC4) and 2688 (CACNA1G)." (PMID 34341417, 2021). "In total, we confirmed 14 genes with glioma-specific splicing; seven were novel events identified by the exon expression array (A2BP1, BCAS1, CACNA1G, CLTA, KCNC2, SNCB, and TPD52L2)." (PMID 18474104, 2008).
prostate carcinoma (3 papers, 2015 to 2022). A carcinoma that arises from epithelial cells of the prostate gland. "Increased expression of CACNA1G was detected in a broad range of cancer diseases, with CACNA1G in the top 1% of overexpressed genes in synovial sarcoma and in the top 2% in prostate carcinoma." (PMID 26147197, 2015).
Spinocerebellar ataxia 42 (3 papers, 2019 to 2024). "In family H, CACNA1G is predicted to be the most disease relevant seed gene because it maps to Spinocerebellar ataxia 42 (SCA42) in OMIM (OMIM 616795)." (PMID 31404076, 2019).
Anxiety (2 papers, 2022 to 2025). Intense feelings of nervousness, tension, or panic often arise in response to interpersonal stresses. "Hence, it appears that the intra-thalamic injection of Cacna1g shRNA did not alter the anxiety-related behaviors or general motor abilities of the mice." (PMID 40332044, 2025).
autosomal dominant cerebellar ataxia (2 papers, 2020 to 2025). A clinically and genetically heterogeneous group of neurodegenerative diseases characterized by a slowly progressive ataxia of gait, stance and limbs, dysarthria and/or oculomotor disorder, due to cerebellar degeneration in the absence of coexisting diseases. "Using linkage analysis and whole-exome sequencing, CACNA1G was linked to an autosomal dominant cerebellar ataxia (ADCA) phenotype in three families, supporting its implication in spinocerebellar ataxia SCA42." (PMID 32638069, 2020).
diabetes (2 papers, 2016 to 2020). "Previous studies have reported upregulation of Cacna1g in ventricle from the Goto-Kakizaki rat, an experimental model of type 2 diabetes mellitus, and the Zucker diabetic fatty rat." (PMID 27096430, 2016).
esophageal cancer (2 papers, 2017 to 2025). A primary or metastatic malignant neoplasm involving the esophagus.
idiopathic generalised epilepsies (2 papers, 2014 to 2023). "Mutations in the CaV3.1 α1 subunit gene CACNA1G have been implicated in idiopathic generalized epilepsy (IGE) susceptibility." (PMID 24592212, 2014). "Mutations in the Cav3.1-encoding gene CACNA1G and Cav3.2-encoding gene CACNA1H are associated with idiopathic generalised epilepsies in humans." (PMID 37082241, 2023).
pancreatic cancer (2 papers, 2015 to 2024). "CpG island methylator phenotype (CIMP)-high status [three/four or more methylated promoters among CACNA1G, CDKN2A, IGF2, and RUNX3] was observed in 12% (34/283) of the pancreatic cancer cases." (PMID 25797243, 2015).
type 2 diabetes (2 papers, 2016 to 2024). "They found that several genetic variants in the CACNA1G gene were significantly associated with an increased risk of type 2 diabetes, suggesting a potential role for CACNA1G in the development of the disease." (PMID 38874740, 2024). "The involvement and change of gene expression of CACNA1G, IGF2, MLH1, and SOCS1, in addition to causing CRC, can cause diseases such as type 2 diabetes, Fanconi’s anemia, and toxoplasmosis." (PMID 38874740, 2024).
anaplastic large cell lymphoma (1 paper, 2022). Anaplastic large cell lymphoma (ALCL) is a rare and aggressive peripheral T-cell non-Hodgkin lymphoma, belonging to the group of CD30-positive lymphoproliferative disorders, which affects lymph nodes and extranodal sites. "On the other hand, downregulation of CACNA1C transcripts (coding for CaV1.2) was seen in centroblastic lymphoma, CACNA1F (coding for CaV1.4) in anaplastic large cell lymphoma, and CACNA1G (coding for CaV3.1) in mantle cell lymphoma." (PMID 36330491, 2022).
Cerebellar hypoplasia (1 paper, 2023). Cerebellar hypoplasia is a descriptive term implying a cerebellum with a reduced volume, but a normal shape and is stable over time. "Seven probands carry causative variants in well-known genes associated with CA or cerebellar hypoplasia: SETX, CACNA1G, CACNA1A, CLN6, CPLANE1, and TBCD." (PMID 38003592, 2023).
coloboma (1 paper, 2009). An abnormality in which a part of a structure in one or both eyes is missing. "The results of profiling alternative splicing of Cacna1g in the tottering, lethargic, stargazer, and Coloboma revealed unaltered splicing regulation of Cacna1g transcripts." (PMID 19480703, 2009).
colorectal adenoma (1 paper, 2024). An adenoma that arises from the colon or rectum. "Among the down-regulated genes, the researchers identified IGF2, SOCS1, MLH1, and CACNA1G as being significantly decreased in colorectal adenoma tissue samples." (PMID 38874740, 2024).
hereditary cerebellar ataxia (1 paper, 2018). Cerebellar ataxia that is transmitted from parent to child. "In addition, CACNA1G is expressed in the cerebellum and variants in the CACNA1G gene are associated with a hereditary cerebellar ataxia." (PMID 32714589, 2018).
keratoconus (1 paper, 2025). A degenerative, structural disorder of the eye, characterized by a cone-shaped protrusion of the cornea. "In the corneal samples of patients with keratoconus, calcium voltage-gated channels including CACNA1C, CACNA1G, CACNA2D1, and CACNA2D4 were found to be down-regulated that could be indicative of reduced cell proliferation as observed in keratoconus." (PMID 39420106, 2025). "As a consequence, down-regulated voltage-gated calcium channels in CACNA1C, CACNA1G, CACNA1D1, and CACNA2D4, and purinergic receptors P2RX1 along with the down- regulated transcription factors including JUN and MYC can be attributed to reduced cell proliferation in keratoconus." (PMID 39420106, 2025).
Myoclonus (1 paper, 2024). Very brief, involuntary random muscular contractions occurring at rest, in response to sensory stimuli, or accompanying voluntary movements. "This case expands the knowledge regarding CACNA1G-associated phenotype and highlights the importance of genetic screening in myoclonus-ataxia disorders." (PMID 39287920, 2024).
tumor (20 papers, 2008 to 2025). "Notably, studies from cancer research that identified the cacna1g gene encoding Cav3.1 as a tumor suppressor gene point in this direction." (PMID 35408817, 2022). "This study investigates our DNA methylation-based PC biomarker panel (ADAMTS1, BNC1, and CACNA1G genes) in differentiating IPMN-advanced neoplasia from IPMN-LGDs." (PMID 36803844, 2023). "Several of those genes are known tumor suppressors that are hypermethylated in solid cancers (CACNA1G, IRF6, ITGA9, and PPP2R2C) and used as biomarkers related to adverse outcome." (PMID 30285865, 2018). "While there is no consensus on a gene panel to determine the CIMP status of a tumour, one of the most commonly used is the Weisenberger panel of genes comprising of CACNA1G, NEUROG1, RUNX3, SOCS1 and IGF2." (PMID 28351398, 2017). "The inactivation of CACNA1G in particular neoplasms suggests that it may play a role as a tumor suppressor gene in such tumors." (PMID 32046241, 2020). "To compare the CIMP classifications derived from our clustering analysis to those derived from the Weisenberger panel of genes, we analysed the methylation status of our tumour samples using MethyLight at each gene from this panel (CACNA1G, NEUROG1, SOCS1, IGF2, RUNX3)." (PMID 28351398, 2017). "Interestingly, some of these genes have been previously associated with CIMP in other tumor types, such as p73, GSTP1, SOCS-1, CACNA1G, CRABP1, NEUROG1 and RUNX3." (PMID 20830311, 2010). "VCGG channels, including CACNA1C, CACNA1D, CACNA1F, CACNA1E, CACNA1A, CACNA1G, CACNA1I, showed significantly higher expression in KIRC than normal cases, whereas CACNA1S and CACNA1H showed higher expression in normal than tumor cases." (PMID 36588677, 2022). "The additional role of CACNA1G and IGF2 warrants further studies, both to investigate tumor-regulating mechanisms and to confirm the clinical role in larger patient samples." (PMID 25879218, 2015). "Others genes in this cluster were targets of estrogen action (e.g. T-type calcium channel subunit; CACNA1G), capable of binding estrogen receptor alpha (FASN, SNCG), or involved in tumor suppression (PRKCD, RASL11A)." (PMID 18941504, 2008).
cancer (9 papers, 2003 to 2025). A tumor composed of atypical neoplastic, often pleomorphic cells that invade other tissues. "MINT31 (also known as CACNA1G) has been mapped to a location of frequent LOH in cancer, and was found to be part of a gene encoding a T-type calcium channel." (PMID 12569385, 2003). "Further, normal function of CACNA1G affects cell proliferation and apoptosis, and disturbing this calcium signaling might be important in cancer, as these processes guide further progress in cellular life." (PMID 25879218, 2015). "In CRC, CACNA1G inactivation may play a role in cancer development by modulating calcium signaling, which potentially affects cell proliferation and apoptosis." (PMID 25594007, 2014).
adenocarcinoma (3 papers, 2010 to 2017). A common cancer characterized by the presence of malignant glandular cells. "Methylation rates for ID4, DCL1, BNIP3, H2AFX, CACNA1G and TIMP3 were significantly different between squamous and adenocarcinomas." (PMID 20849603, 2010).
neurodevelopmental disorder (3 papers, 2024 to 2025). A behavioral and cognitive disorder with onset during the developmental period that involves impaired or aberrant development of intellectual, motor, or social functions. "Both CACNA1D and CACNA1G, which show high level of expression in the cerebellum, have been previously implicated in neurodevelopmental disorders." (PMID 41442065, 2025). "Also, we have identified 15 de novo variants in genes that were previously implicated in ASD or related neurodevelopmental disorders (PHF21A, WASF1, TCF20, DEAF1, MED13, CREBBP, KDM6B,SMURF1, ADNP, CACNA1G, MYT1L, KIF13B, GRIA2, CHM, and KCNK9)." (PMID 38572415, 2024).
psychiatric diseases (3 papers, 2020 to 2025). "Mutations in genes encoding Cav3 channels (CACNA1G, CACNA1H, and CACNA1I) have been linked to a variety of neurodevelopmental, neurological, and psychiatric diseases designated here as neuronal Cav3 channelopathies." (PMID 32638069, 2020).
metabolic disorders (2 papers, 2017 to 2022). "Notably, four of seven methylation loci were located in coding genes (ANK3, CDKN2B, CACNA1G) and the miRNA let-7b host gene (MIRLET7BHG) that have been previously implicated in metabolic disorders in human adults and animal model systems." (PMID 28264723, 2017).
movement disorder (2 papers, 2009 to 2024). Neurological conditions resulting in abnormal voluntary or involuntary movement, which may impact the speed, fluency, quality and ease of movement.
gastrointestinal disease (1 paper, 2017). A disease that occurs in the gastrointestinal system, excluding the hepatobiliary system. "Taken together, our data suggest that Cacna1g exclusively expressed in serosal PDGFRα+ cells is a new pathological marker for gastrointestinal diseases." (PMID 28806761, 2017).
CACNA1G also shares sentences with these, for which no sentence is quoted: cerebellar ataxia (5 papers); neurological disorders (5); Parkinson disease (5); AV block (3); depression (3); developmental delay (3); Hypertension (3); Obesity (3); autism (2); Crohn disease (2); diverticulitis (2); glioblastoma (2); hypertrophy (2); infection (2); microcephaly (2); Timothy syndrome (2); Ventricular arrhythmia (2); acral lentiginous melanoma (1); adenocarcinoma of the lung (1); alcoholism (1); asthma (1); atrial tachycardia (1); bipolar disorder (1); Bordetella Infections (1); brain disorder (1); cardiovascular disease (1); cerebral infarction (1); cocaine dependence (1); cognitive disorder (1); colorectal polyps (1).
A further 46 diseases each share a sentence with CACNA1G in 1 paper.